MYOD1 (myogenic differentiation 1)
Diseases named in the same sentence as MYOD1 in open-access papers (continued):
Sharing a sentence is not in itself a finding about the gene and the disease.
infection (18 papers, 2004 to 2023). The state of being infected such as from the introduction of a foreign agent such as serum, vaccine, antigenic substance or organism. "UDCs from healthy individuals were infected with the MYOD1-retroviral vector at a multiplicity of infection (MOI) of 200 in growth medium, and subsequently, MYOD1-positive cells were selected by adding 1 μg/mL puromycin to the medium." (PMID 30846748, 2019). "Compared to sh-NC, sh-DGAT2 infection of BSCs significantly inhibited the mRNA expression of PAX7, MYOD1, MYOG, and MYR4 (p < 0.05)." (PMID 35883393, 2022). "Infection of BAF60C2 lentivirus alone cannot activate the myogenic program in the absence of MYOD1." (PMID 28491098, 2017).
myopathy (7 papers, 2012 to 2024). A disease of the muscle in which the muscle fibers do not function properly. "This, coupled with the absence of a regeneration response driven by an increase in PAX7, MYOD1 and myogenin, apparently cause the slow, progressive myopathy observed in Sil1Gt mice." (PMID 29666155, 2018).
metabolic disorders (1 paper, 2021). "Considering the significant role of adipocyte differentiation in the formation and function of adipose, clarification of the mechanism of MYOD1-mediated regulation of adipocyte differentiation is essential for exploring strategies for the treatment of metabolic disorders, including white striping." (PMID 33952351, 2021).
MYOD1 also shares sentences with these, for which no sentence is quoted: sarcopenia (19 papers); Cachexia (10); Atrophy (7); lymphoma (5); synovial sarcoma (5); prostate carcinoma (4); Arthritis (3); channelopathy (3); muscle disorders (3); Skeletal muscle atrophy (3); vitamin D deficiency (3); childhood cancer (2); colon adenocarcinoma (2); dermatomyositis (2); diabetes (2); Ewing sarcoma (2); glioblastoma (2); Insulin resistance (2); liver fibrosis (2); myonecrosis (2); neuromuscular disease (2); non-small cell lung carcinoma (2); osteosarcoma (2); POMPE disease (2); retinoblastoma (2); skeletal muscle disorder (2); Stress urinary incontinence (2); Wilms tumor (2); acute lymphoblastic leukemia (1); age (1).
A further 91 diseases each share a sentence with MYOD1 in 1 paper.